B4GALT6 (beta-1,4-galactosyltransferase 6)
Description:
Catalyzes the synthesis of lactosylceramide (LacCer) via the transfer of galactose from UDP-galactose to glucosylceramide (GlcCer). LacCer is the starting point in the biosynthesis of all gangliosides (membrane-bound glycosphingolipids) which play pivotal roles in the CNS including neuronal maturation and axonal and myelin formation (By similarity).
Synonyms: Beta4Gal-T6; b4Gal-T6; beta4GalT-VI
Tractability: Antibody: UniProt predicts a signal peptide or a membrane-spanning region.
Gene: Protein-coding gene on chromosome 18 (31,621,911 to 31,685,836, reverse strand). Ensembl gene ENSG00000118276.
Subcellular location: Golgi apparatus, Golgi stack membrane
Pathways (Reactome):
Metabolism: Glycosphingolipid biosynthesis; Keratan sulfate biosynthesis
Metabolism of proteins: N-Glycan antennae elongation; O-linked glycosylation of mucins
Gene Ontology:
Molecular function: galactosyltransferase activity; protein binding; UDP-galactose:glucosylceramide beta-1,4-galactosyltransferase activity; glycosyltransferase activity
Biological process: lactosylceramide biosynthetic process; central nervous system myelination; central nervous system neuron axonogenesis; ganglioside biosynthetic process; glycosphingolipid biosynthetic process; neuron maturation; carbohydrate derivative biosynthetic process; carbohydrate metabolic process
Cellular component: Golgi apparatus; Golgi membrane; Golgi cisterna membrane
Genetic constraint (gnomAD): Loss-of-function variants: 10 observed, 32.11 expected, observed/expected ratio (o/e) 0.31, 90% interval 0.19 to 0.53. The upper end of that interval is the gene's LOEUF score, 0.53, which puts it in group 2 of 6, group 1 being the genes least tolerant of losing a copy. Missense variants: 306 observed, 391.26 expected, observed/expected ratio (o/e) 0.78, 90% interval 0.71 to 0.86. Synonymous variants: 130 observed, 134.76 expected, observed/expected ratio (o/e) 0.96, 90% interval 0.84 to 1.12.
Homologues: Orthologues: chimpanzee B4GALT6 (99% identical), macaque B4GALT6 (99% identical), rabbit B4GALT6 (99% identical), pig B4GALT6 (99% identical), dog B4GALT6 (98% identical), guinea pig B4GALT6 (97% identical), mouse B4galt6 (95% identical), rat B4galt6 (94% identical), tropical clawed frog b4galt6 (80% identical), zebrafish b4galt5 (66% identical). Paralogues in human: B4GALT5 (72% identical), B4GALT3 (35% identical), B4GALT2 (34% identical), B4GALT1 (33% identical), B4GALT4 (31% identical), B4GALT7 (25% identical).
Diseases named in the same sentence as B4GALT6 in open-access papers:
B4GALT6 is named in the same sentence as 12 diseases in open-access papers, as found by Europe PMC text mining. Sharing a sentence is not in itself a finding about the gene and the disease. The quoted sentences say what the papers report.
cholestasis (1 paper, 2025). Impairment of the bile flow caused by obstruction within the liver, or outside the liver in the bile duct system. "Our ongoing study found that B4galt6, LacCERs, and GluCERs were elevated in mice with cholestasis." (PMID 40025008, 2025).
depression (1 paper, 2023). "B4GALT6 gene, found to be significant in half of the models, has been reported to be related to depression severity." (PMID 37680967, 2023).
experimental autoimmune encephalomyelitis (1 paper, 2025). An autoimmune demyelinating disease of the central nervous system that is produced experimentally in animals by the injection of homogenized brain or spinal cord in Freund's adjuvant. "LacCer synthesis is catalyzed by beta-1,4-galactosyltransferase 6 (B4GALT6), whose expression is controlled by NF-κB and upregulated in astrocytes in experimental autoimmune encephalomyelitis (EAE) in non-obese diabetic mice." (PMID 40538417, 2025).
ovarian carcinoma (1 paper, 2014). A malignant neoplasm originating from the surface ovarian epithelium. "One branch clustered eight genes (NAGA, B4GALT6, HEXA, GLB1, GBA, GLA, UGCG, HEXB) with generally comparable expression levels among the cell lines, except for the UGCG gene which was expressed at considerably higher levels in both HOSE cell lines compared with the ovarian cancer cell lines." (PMID 25294702, 2014).
prostate tumors (1 paper, 2020). "In contrast, mRNA expression of enzymes involved in the biosynthesis of glycosphingolipids, including glucosylceramide synthase (UCGC), and lactosylceramide synthases B4GALT5 and B4GALT6, were elevated in CAV1-high prostate cancer cell lines and prostate tumors." (PMID 32855410, 2020).
type 2 diabetes (1 paper, 2025). "The protein encoded by the second genome-wide significant locus (B4GALT6) catalyses the synthesis of ceramides and has been shown to be associated with type 2 diabetes." (PMID 40025146, 2025). "Both ADAMTS16 and B4GALT6 are implicated in the development of type 2 diabetes." (PMID 40025146, 2025).
cancer (2 papers, 2016 to 2022). A tumor composed of atypical neoplastic, often pleomorphic cells that invade other tissues. "In contrast to this ambiguity, the GlycoEnzOnto ontology suggests that the impact of cancer is likely to be more severe on lactosylceramide biosynthesis initiating enzymes: A4GALT5, B3GALT5, B3GNT5 and B4GALT6." (PMID 36282863, 2022). "In the cases of B4GALT6 and B4GALT7, no knowledge is available for their relevance to cancers." (PMID 27092876, 2016).
infection (1 paper, 2017). The state of being infected such as from the introduction of a foreign agent such as serum, vaccine, antigenic substance or organism. "Surprisingly, infection with SV40 was also increased when B4GALT5 or B4GALT6 was inhibited, even though GM1a synthesis is downstream of LacCer synthesis." (PMID 28388693, 2017).
tumours (1 paper, 2022). "LGALS1, B4GALT6, and GALNT11 were upregulated and MGAT5, MAN1A1, MANBA, LUM, GALNT1 and 7, HAPLN3, and ST6GALNAC5 were downregulated in Fra-2 cl 1 select primary tumours, while MGAT4A was upregulated." (PMID 34693476, 2022).
B4GALT6 also shares sentences with these, for which no sentence is quoted: asthma (1 paper); gout (1); Stroke (1).